Y_RNA (Y RNA )
Gene: Miscellaneous RNA gene on chromosome 4 (145,958,128 to 145,958,240, reverse strand). Ensembl gene ENSG00000201314.
Homologues: Orthologues: chimpanzee Y_RNA (99% identical), macaque Y_RNA (93% identical). Paralogues in human: RNY1P11 (86% identical), RNY1 (85% identical), Y_RNA (85% identical), Y_RNA (84% identical), Y_RNA (83% identical), Y_RNA (82% identical), Y_RNA (81% identical), RNY1P5 (80% identical), Y_RNA (80% identical), RNY1P10 (79% identical), RNY1P8 (79% identical), Y_RNA (79% identical), and 94 more.